IL6 (interleukin 6)
Diseases named in the same sentence as IL6 in open-access papers (continued):
Sharing a sentence is not in itself a finding about the gene and the disease.
allergic asthma (continued). "Pro-inflammatory cytokines (IL-1 and IL-6) are known to intensify the inflammatory cascade and to improve vascular penetrability, which can lead to the formation of pulmonary edema in allergic asthma." (PMID 33322573, 2020). "Since macrophages constitute the predominant fraction of IL-6 producing cells in the lungs, we evaluated the contribution of IL-6 from macrophages to the development of allergic asthma using reverse genetics approach." (PMID 30534125, 2018). "The murine model for HDM-induced allergic asthma showed elevated pulmonary IL-6 concentrations, which is in line with human studies that showed elevated IL-6 levels in BALF, sputum and serum from asthmatic patients." (PMID 26003185, 2016). "Proinflammatory cytokines, such as IL-1 and IL-6, amplify inflammatory response and increase the vascular permeability, both of which participate in the development of pulmonary edema in allergic asthma." (PMID 23710463, 2013). "Although Yokoyama and coworkers have reported that patients with stable allergic and non-allergic asthma exhibited an increase in circulating IL-6, our results show comparable IL-6 levels in all study groups." (PMID 23565268, 2013). "We also evaluated the production of cytokines (IL-12 p40, IL-12 p70, IL-6, IL-23, and IL-10) in MD-DCs from allergic asthma children, and found that PS-G alone stimulated Der p 1-pulsed DCs to secrete IL-12 p40, IL-12 p70, IL6, IL23, and IL-10." (PMID 21612588, 2011). "The presence of PS-G in an allergen pulse promoted allergic MD-DCs to produce IL-12 p70, IL-12 p40, IL-6, IL-23, and IL-10, and exerted an effect on shifting the immune balance towards Th1 in children with allergic asthma." (PMID 21612588, 2011). "Pro-inflammatory factors such as IL-5, IL-13, TNF-α, and IL-6 play a leading role in the pathogenesis of allergic asthma, including the growth of eosinophils, the isotypic transition of B cells to IgE production, chemotaxis of neutrophils, and bronchial contraction." (PMID 39408735, 2024). "In the overweight/obese group, interleukin‐6 (IL‐6) was associated with non‐allergic asthma but not allergic asthma." (PMID 36973952, 2023). "In addition, interleukin-6 (IL-6) and IL-17F were downregulated after treatment with VA extracts in an allergic asthma model." (PMID 37509556, 2023). "IL-1β and IL-6 were two inflammatory factors related to allergic asthma." (PMID 35431951, 2022). "We, thus, expected that IL-6 from dendritic cells may be the main factor determining the severity of Th2 responses to HDM in allergic asthma model." (PMID 30534125, 2018). "Besides being released by macrophages and T cells, IL-6 is highly expressed by epithelial cells obtained from allergic asthma patients." (PMID 25849971, 2015). "Furthermore, our data also suggests that IL-6 contributes to impaired lung function in allergic asthma." (PMID 20205953, 2010). "Future studies should incorporate direct home radon measurements, comprehensive endotyping panels, and longitudinal biomarker sampling to validate these findings and elucidate whether IL-6 trans-signaling pathways mediate radon-induced airway injury in non-allergic asthma." (PMID 42188340, 2026). "Furthermore, as the pharmacological inhibition of IL-6 together with TNF has been suggested to be beneficial for patients suffering from severe allergic asthma, it is also interesting to mention that the complete formulation of 2LALERG® also encompasses ULD of TNF-α." (PMID 38541700, 2024). "During a cytokine storm, immune and non-immune cells would release a large number of pro-inflammatory cytokines, including IL-6, tumor necrosis factor-α (TNF-α), and chemokines, which would cause substantial damage to the host immune response and further induce various ADs such as allergic asthma." (PMID 38263182, 2024). "Therefore, the approach of cell type-restricted targeting of IL-6 may be effective in the treatment of allergic asthma, especially its severe neutrophilic type." (PMID 30534125, 2018).
allergic asthma (continued). "Thus, in mild-moderate allergic asthma there is no clear association between IL-6 and the IL-17/neutrophils axis." (PMID 20205953, 2010). "Undoubtedly, the significance of elevated sputum IL-6 in allergic asthma remains unclear." (PMID 20205953, 2010). "Especially in neuroinflammation, studies have reported a reduction in the production of cytokines, such as IL-1β, IL-6, TNF-α, IL-12, and IL-17, and chemokines, such as IFN-Ɣ, MCP-1, MIP-1a, and MIP-1b in allergic asthma." (PMID 40243683, 2025). "In the BAL of patients with non-allergic asthma, we measured decreased concentrations of IL-4, IL-8, IL-13, IFN-γ, C4a, C5a, and MCP-1 and increased concentrations of IL-6, IL-12p70, TNF-α, and C3a." (PMID 40725075, 2025). "Previous studies have indicated that within the lungs of mice with allergic asthma, DCs can activate the JAK/STAT3 signaling pathway by secreting IL-6, thereby promoting the differentiation and activation of Th2 and Th17 cells." (PMID 39078462, 2024). "The role of IL-4, IL-5, IL-6, IL-33, TNF-α and IFN-γ in the pathogenesis of allergic asthma is well documented has been elaborately explicated elsewhere." (PMID 38807596, 2024). "With the additional control of lung IL-1β, IL-6, and TNF-α levels after OVA inhalation exposure, trifuhalol A has strong potential to be further evaluated as a therapeutic candidate for allergic asthma." (PMID 37998734, 2023). "IL-6 is present at a higher concentration in the serum and BALF of patients with allergic asthma, and the concentration is negatively correlated with FEV1." (PMID 33708257, 2021). "Inflammatory cytokine secretion, such as IL-6 and TNF-α, is commonly regarded as an important indicator that reflects the severity of BMMC activation and OVA-induced allergic asthma." (PMID 34421593, 2021). "Morin treatment downregulated the expression of BLT2, NF-κB, and Th2-cytokine (IL-1β, IL-4, IL-6, IL-13, and TNF-α) in the lungs of an allergic asthma rat model." (PMID 33917985, 2021). "Further, BHT down-regulated expression levels of pro-inflammatory cytokines, such as TNF-α, IL-1β, IL-6, IL-8 and IL-17A indicating that BHT has an effect on declining pro-inflammatory response for allergic asthma." (PMID 32397290, 2020). "It shows ability to inhibit the production of inflammatory mediators, such as IL-1β, IL-6, and TNF-α in macrophages and in mice with allergic asthma." (PMID 30809149, 2019). "In allergic asthma, TLR7 activated pDC produce less IL-6, IFN-α, and TNF than pDC from healthy people." (PMID 29118754, 2017). "Furthermore, IL-6 may contribute to impaired lung function in allergic asthma." (PMID 20205953, 2010). "Increased levels of inflammatory markers including cytokines such as interleukins (IL-6), chemokines such as IL-8 and other inflammatory mediators such as PGE2 by airway epithelial cells are the hallmarks of inflammatory response in allergic asthma." (PMID 19657391, 2009). "Generally, cytokines play a central role in the pathogenesis of allergic inflammation, with related studies documenting that both pro-inflammatory cytokines and chemokines, including TNF-α, IL-6, NO, and CXCL8, contribute to the pathogenesis and exacerbation of allergic asthma." (PMID 33261109, 2020). "It reduced the IL-1β, IL-6, TNF-α, and TGF-β level in OVA-induced allergic asthma both in antibiotic-free and antibiotic-treated mice notably, indicating an anti-inflammatory effect in the OVA-induced allergic asthma model." (PMID 33456673, 2020). "Furthermore, a recent study revealed that the inhibition of IL-6 and TNF-α could assist in the prevention of allergic asthma in a mouse model." (PMID 36501052, 2022). "IL-17 and IL-6 levels were significantly higher in plasma of children with allergic asthma than in those of the healthy control children (P < 0.01, P < 0.01), while TGF-β and IL-10 expression levels were markedly lower in the allergic asthma group than in the healthy control group (P < 0.01)." (PMID 32834826, 2020).
allergic asthma (continued). "However, the exact mechanism of IL-6 involvement in the pathogenesis of allergic asthma has not been determined previously, and the IL-6-producing cell types that make the most significant contribution to the development of airway hyper-reactivity and inflammation have not been established." (PMID 30534125, 2018). "In addition, CD86 siRNA treatment did not stimulate systemic production of IL-6 or IFN-β, suggesting that CD86 may become a promising target for the treatment of allergic asthma." (PMID 25344652, 2014).
E. coli infection (72 papers, 2013 to 2026). "Studies have confirmed that the mRNA expression of TNF-α, IL-6, IL-8, and other cytokine genes was increased in intestinal tissues of weaned piglets caused by E. coli infection." (PMID 35571917, 2022). "The results of the current study showed that nicotinic acid supplements in the diet could ameliorate inflammation by down-regulated the expression of TNF-α, IL-6, and IL-8 in piglets caused by E. coli infection." (PMID 35571917, 2022). "A similar effect of IL6 has been observed in previous reports, which showed that mice with IL6 deficiency exhibited more severe Escherichia coli infections, and inhibition of IL6 signaling increased the survival of intracellular Brucella abortus in macrophages and decreased the production of TNF–α." (PMID 34439908, 2021). "E. coli infection caused an acute suppurative inflammation in the lung with increased lung index and serum TG and TC contents; elevated pulmonary tumor necrosis factor-α, interleukin (IL)-1β, IL-6, IL-8, and leptin levels; and oxidative stress in mice." (PMID 30250258, 2018). "Instead, E. coli infection triggered a robust response in the endothelial cells, as evident by elevated levels of IL-6, CCL2, and CX3CL1." (PMID 41408425, 2026). "After 9 h, PGD2 treatment significantly increased TNF-α, IL-1β, IL-6, and IL-8 levels compared to the E. coli infection group, while IL-10 levels decreased." (PMID 40874199, 2025). "E. coli infection induced IL-6 expression, which was reversed by Weissella supplementation, confirming its modulatory effect on IL-6 production." (PMID 41256842, 2025). "E. coli infection increased the expression of pro-inflammatory cytokines (Il-6 and Il-1β, all p<0.05) in leukocytes from MLN (control mice)." (PMID 38728303, 2024). "To determine why U2AF1-S34F mice succumbed to E. coli infection, we monitored the production of the pro-inflammatory cytokines TNFα and IL-6 in the peritoneum and blood after peritoneal E. coli infection." (PMID 37591942, 2023). "E. coli infection also induced a significant increase in IL-6 secretion compared to the control cells (p < 0.05)." (PMID 37835613, 2023). "From the review of existing research, the F18+ E. coli infection triggers intestinal inflammation, resulting in elevated IL6 (60%), IL8 (43%), and TNF-α (28%), increasing oxidative damages, and causing a 14% reduction in villus height." (PMID 37685055, 2023). "According to previous studies, pigs with F18+ E. coli infection have increased concentrations of IL6 (60%), IL8 (43%), and TNF-α (28%) in the small intestine of nursery pigs." (PMID 37685055, 2023). "Attenuation of E. coli infection by isoleucine through the modulating antimicrobial peptide expression as well as its effect on plasma level of endotoxin and IL6 in weaned pigs also were reported." (PMID 35915604, 2022). "In pigs, increased expression of pro-inflammatory cytokines IL-1β and IL-6 after Escherichia coli infection have been found, which was demonstrated to trigger mucin release and MUC gene expression." (PMID 34072321, 2021). "It was reported that Gln can increase IL-6 and SIgA concentrations and protect against Escherichia coli infection via intestinal innate immunity in mice." (PMID 34046146, 2021). "E. coli infection triggered a massive increase in transcript levels for Ccl2, iNos or Il6, a modest increase in Il10 transcripts but totally abrogated IL4 transcript expression in both Sham- and CLP-operated mice." (PMID 32425929, 2020). "Previous studies have shown that the release of these cytokines, such as TNF-α, IL-6, and IL-1β, was induced by LPS during Escherichia coli infection." (PMID 33134350, 2020). "Up-regulation of interleukin (Il)-1β, Il-6, Il-8, Il-18, tumor necrosis factor alpha, and chemokine Cxcl2 expression after E. coli infection was attenuated by L. johnsonii L531." (PMID 32823867, 2020).
E. coli infection (continued). "Reproductive tract immune responses to E. coli infection require the binding of lipopolysaccharide from E. coli to toll-like receptor 4 on the surface of epithelial cells, which then produce IL-6." (PMID 30923927, 2019). "E. coli infection markedly increased the mRNA levels of IL-6 and TNF-α, but such increases were prevented by the C. militaris mycelium producing Mag II-CB." (PMID 29402269, 2018). "Our previous study has showed that IL-1β, IL-6, and IL-8 in duck and DEFs increase somewhat after E. coli infection." (PMID 30349536, 2018). "In this study, we examined the effect of E. coli infection on the expression of the pro-inflammatory cytokines IL-1β, IL-6, and TNF-α in PRNP-knockout macrophages." (PMID 25058617, 2014). "However, concentration-dependent effects were observed: in E. coli infection, IL6 was upregulated in E1 while CSF2 (granulocyte-macrophage colony-stimulating factor) was upregulated in E3." (PMID 40771952, 2025). "However, at 12 and 24 h post-infection, PGD2 significantly downregulated the secretion of TNF-α, IL-1β, and IL-8 compared to the E. coli infection group, while the secretion of IL-6 and IL-10 remained elevated (P < 0.01)." (PMID 40874199, 2025). "Furthermore, IL-6 plays an essential role in protecting mice from Escherichia coli infection by efficiently inducing neutrophils in the bloodstream." (PMID 40109962, 2025). "Systemic E. coli infection induced substantial increases in IL-6, IFN-γ, TNF-α, and IL-1β." (PMID 41309396, 2025). "Previous studies have shown that taking BBR can significantly alleviate the increase in serum IL-6, IL-1β, and TNF-α caused by Escherichia coli infection in chicks and alleviate the increase in IL-6, IL-8, and TNF-α expression in the intestine caused by Escherichia coli infection in weaned piglets." (PMID 40829428, 2025). "Our results showed that the upregulation of IL6 was particularly abnormal during E. coli infection." (PMID 38368261, 2024). "Furthermore, the attenuated inflammatory response in hyperglycemic placenta was pathogen-specific, with the suppression of TNF-α and IL-6 or IL-1β after S. agalactiae and E. coli infection, respectively." (PMID 36982317, 2023). "Remarkably, the double challenge of high glucose and infection provoked a pathogen-specific attenuated placental inflammatory response in the hyperglycemic condition, mainly denoted by reduced TNF-α and IL-6 secretion after S. agalactiae infection and by IL-1β after E. coli infection." (PMID 36982317, 2023). "Moreover, the protein levels of IL-1β and IL-6 were lower and located in the superficial umbrella cells in diabetic mice bladders 24 h post E. coli infection." (PMID 36127330, 2022). "Clinically source MDR E. coli strains infection caused serious systemic inflammatory response by sharply increasing the serum proinflammatory cytokines, such as TNF-α, IFN-γ, IL-6 (P < 0.05), and a significant reduction in IL-4 levels (P < 0.05) compared with the control group." (PMID 35250983, 2022). "The expression of TLRs in BF of chicks treated with HQD were up-regulated, indicating that HQD regulates the anti-infection ability by increasing the mRNA levels of TLR4, -5 and -15, further decreasing the serum LZM and IL-1β, TNF-α, IL-10, IL-6 level of chicks suffered E. coli infection." (PMID 36198724, 2022). "However, neutrophilic PTGS2 expression and IL6 expression in the amnion is differentially induced by E. coli infection." (PMID 34495952, 2021). "In a mouse model for S. aureus and E. coli infections, animals with E. coli infection showed significantly greater serum levels of the cytokines interleukin (IL)-1α, IL-1β, IL-6, monocyte chemotactic protein (MCP)-1, and macrophage inflammatory protein (MIP)-1α than S. aureus-infected mice." (PMID 34247606, 2021). "In this study, E. coli infection increased the concentration of IL-6 and TNF-α, suggesting that E. coli could induce inflammation in mice through IL-6 and TNF-α production." (PMID 28798800, 2017).